C9orf72 (C9orf72-SMCR8 complex subunit)
Diseases named in the same sentence as C9orf72 in open-access papers (continued):
Sharing a sentence is not in itself a finding about the gene and the disease.
neurodegenerative disease (117 papers, 2012 to 2026). A disorder of the central nervous system characterized by gradual and progressive loss of neural tissue and neurologic function. "Defects in late state autophagy and lysosomes have often been linked to neurodegenerative diseases, including in C9orf72 expansion models." (PMID 37733679, 2023). "Taken together our study provides a molecular mechanism for the derailment of protein homeostasis by PR repeat polymers in C9orf72-associated neurodegenerative diseases." (PMID 34099711, 2021). "Here we provide insight into the molecular mechanism of impaired chaperone activity and derailed protein homeostasis by PR repeat polymers in C9orf72-associated neurodegenerative diseases." (PMID 34099711, 2021). "In this review article, we provide a conceptual framework for assessing the putative involvement of C9orf72 as a synaptopathy, and we explore the underlying and common disease mechanisms with other neurodegenerative diseases." (PMID 34140881, 2021). "The combined data establish a toxic mechanism that is specific for proline/arginine dipeptide repeat polymers and leads to derailed protein homeostasis in C9orf72-associated neurodegenerative diseases." (PMID 34099711, 2021). "Because glial cells have been pinpointed as potential contributors to neurodegenerative diseases, elucidating their role in C9orf72 HRE-associated FTLD and ALS is necessary." (PMID 33123074, 2020). "Structural variants within the genome can play a significant role in neurodegenerative disease risk, such as the repeat expansion in C9orf72 and the tri-nucleotide repeat in ATXN2, both of which are associated with familial and sporadic ALS." (PMID 32082115, 2020). "Massive expansion of a DNA hexanucleotide sequence repeat (C2G4) within the human C9orf72 gene has been linked to a number of neurodegenerative diseases." (PMID 29912891, 2018). "The repeating (C2G4)n DNA sequence from the human C9orf72 gene is causally linked to the development of a number of neurodegenerative diseases (vide infra)." (PMID 29912891, 2018). "The results presented herein have particular implications for the structure of the (GGGGCC)n repeat expansion in the C9orf72 gene, which is associated with neurodegenerative diseases like ALS and FTD48,49." (PMID 29773796, 2018). "Significant poly‐GP levels were already detectable in asymptomatic C9orf72 mutation carriers compared to healthy controls and patients with other neurodegenerative diseases." (PMID 28408402, 2017). "Altogether, these results suggest that different pathways are implicated in the onset of C9orf72-mediated neurodegenerative diseases." (PMID 28611593, 2017). "We propose that C9orf72 function is important for metabolic control and its deficiency can contribute to the development of neurodegenerative diseases." (PMID 27875531, 2016). "Thus, the modulation of nucleocytoplasmic transport is also a potential therapeutic strategy for C9orf72-linked neurodegenerative diseases." (PMID 38318532, 2024). "Our detection of TDP-43-dependent cryptic peptides in CSF and blood of presymptomatic C9orf72 mutation carriers also aligns with a common theme of neurodegenerative diseases—that pathogenic mechanisms often begin years before the emergence of clinically relevant symptoms." (PMID 38278991, 2024). "Similarly, the link between C9orf72, associated with neurodegenerative diseases and neuronal apoptosis, and IL1B, a pro-inflammatory cytokine, underscores the potential interplay between neurodegeneration and inflammation in PND pathogenesis." (PMID 38481183, 2024). "Furthermore, in literature, other possible neurodegenerative disease entities associated with C9orf72 repeat expansions have been discussed." (PMID 37006326, 2023). "Despite this, CSF poly-GP levels have the potential to be a useful marker to distinguish C9ORF72-associated disease from other neurodegenerative diseases and may aid in the identification of C9ORF72 mutation carriers." (PMID 33679328, 2021).
neurodegenerative disease (continued). "Therefore, in this article, we will review the evidence for C9ORF72 as a causative factor in neurodegenerative diseases, the underlying mechanisms, and the potential for targeting C9ORF72 as a strategy to alleviate neurodegenerative disease progression." (PMID 33390807, 2021). "It has been suggested that RPS25 might be a potential therapeutic target for C9orf72-related neurodegenerative diseases caused by nucleotide repeat expansions, which could support our findings indirectly." (PMID 34225819, 2021). "Overall, our study suggests that modulation of the insulin/IGF signalling pathway could be an effective therapeutic intervention against hexanucleotide repeat extension associated with C9orf72 neurodegenerative diseases, with InR being a genetic modifier." (PMID 33739284, 2021). "However multi-site studies offer a good possibility to investigate rare disorders like neurodegenerative diseases caused by c9orf72 mutation carrier status." (PMID 29599716, 2018). "Since aging is the strongest risk factor for neurodegenerative diseases, differences in the aging process may contribute to the high heterogeneity observed in C9orf72 patients." (PMID 28439722, 2017). "The results suggest that a deficiency in the function of C9orf72 may contribute to the pathogenesis of relevant neurodegenerative diseases." (PMID 27875531, 2016). "Given that autophagy can protect against neurodegenerative disease by preventing accumulation of toxic proteins, disrupting this process by reducing C9ORF72 expression may render cells more susceptible to repetitive RNA and the products of erroneous hexanucleotide repeat translation." (PMID 26979938, 2016). "Intranasal administration of peptide-tagged AELN/RNP complexes in vivo confirmed the successful genome editing of C9orf72, demonstrating the potential of this system for treating neurodegenerative diseases." (PMID 41909467, 2026). "The proteins upregulated across multiple neurodegenerative diseases within cortical layer I include phosphorylated TDP-43 (significant change identified in C9ORF72 and GRN) and phosphorylated tau S214 (significant change identified in AD and MAPT)." (PMID 40476255, 2025). "A.B.S. is a co-applicant on a patent application related to C9orf72, “Method for diagnosing a neurodegenerative disease” (PCT/GB2012/052140)." (PMID 40834859, 2025). "Neurodegenerative disease incidence in C9orf72 HRE carriers has been studied using cohorts from disease-affected families or by extrapolating from population disease incidence, potentially introducing bias." (PMID 40682810, 2025). "H.R.M. is a consult for Aprinoia and AI Therapeutics H.R.M. is a co-applicant on a patent application related to C9orf72, “Method for diagnosing a neurodegenerative disease” (PCT/GB2012/052140)." (PMID 40834859, 2025). "The mechanisms by which C9ORF72 HRE triggers or contributes to the neurodegenerative disease are not yet fully understood." (PMID 40012994, 2025). "For example, antisense oligonucleotides (ASOs) are used to target and degrade aberrant mRNAs associated with various neurodegenerative diseases, such as ALS (targeting SOD1 and C9ORF72)." (PMID 41255704, 2025). "Deficiency in PGRN levels is associated with development of neurodegenerative disease, including FTD subtypes with a mutation in C9ORF72 (TDP type A/B) and in GRN (TDP type B), and is linked to lysosomal dysfunction and TDP-43 aggregation." (PMID 40713859, 2025). "The advancement in C9orf72 ALS/FTD research serves as a valuable reference for exploring RAN translation in other neurodegenerative diseases." (PMID 38628764, 2024). "Similar effects were observed in mammalian cells, suggesting a therapeutic potential in targeting insulin signaling pathways for C9orf72-related neurodegenerative diseases." (PMID 38791099, 2024). "Studies have found that expansions in the hexanucleotide repeat in the C9orf72 gene involve the cerebellum in patients with neurodegenerative diseases such as bvFTD." (PMID 39188506, 2024).
neurodegenerative disease (continued). "In another setback for neurodegenerative diseases, two groups tested an ASO that lowers the sense strand of C9orf72 in patients with familial ALS caused by repeat expansion mutations of the C9orf72 gene." (PMID 39352381, 2024). "According to recent studies, C9orf72 is closely related to the pathogenesis of neurodegenerative diseases." (PMID 37353944, 2023). "The cytoskeleton is widely reported to be disrupted in genetic and sporadic ALS, while defective N/C transport, first described in C9orf72-associated ALS, appears to be a common feature of several ALS subtypes and other neurodegenerative diseases." (PMID 37585529, 2023). "Separately, emerging evidence suggests widespread derepression of transposable elements (TEs) in the brain in several neurodegenerative diseases, including C9orf72 HRE-mediated FTD (C9-FTD)." (PMID 36446586, 2023). "Nucleocytoplasmic transport (NCT) is affected in several neurodegenerative diseases including C9orf72-ALS." (PMID 36494425, 2022). "We described an earlier disease onset in GRN/C9orf72 pedigrees in subjects carrying the p.Asn521Thr variant (rs1043424) in PTEN-induced kinase 1 (PINK1), a gene that is already known to be involved in neurodegenerative diseases." (PMID 36361641, 2022). "In our study, in particular, the pulvinar showed lower values in carriers compared to non-carriers in all clinical syndromes, confirming the specific involvement of this region in C9orf72-related neurodegenerative diseases." (PMID 35326292, 2022). "The best known example of a non-coding repeat expansion leading to a neurodegenerative disease is found in the C9orf72 gene (this will be discussed under “ALS—C9orf72”)." (PMID 32323160, 2020). "C9orf72 related disorders represent a heterogenous group of neurodegenerative diseases, as far as clinical and pathological characteristics are concerned." (PMID 32775019, 2020). "SVs have been implicated in many complex diseases including retinitis pigmentosa (MSR1), Alzheimer’s (TOMM40), frontotemporal dementia (C9orf72), and other neurodegenerative diseases." (PMID 32082115, 2020). "Genes that contribute to FTD include: C9ORF72, FUS, VCP, TDP–43, MAPT/tau, CHMP2B, PGRN, TBK1, and TMEM106B, thus there is overlap with other neurodegenerative diseases including: ALS (C9ORF72, FUS, VCP and TDP–43), AD (tau) and PD (tau)." (PMID 32357532, 2020). "Disruption of nucleocytoplasmic transport is increasingly implicated in the pathogenesis of neurodegenerative diseases, including ALS caused by a C9orf72 hexanucleotide repeat expansion." (PMID 32119645, 2020). "We demonstrate that HARDEN can be applied to the neurodegenerative disease genes C9orf72 and APP, and methylation can be induced via HDR with both single and double stranded methylated repair templates." (PMID 31680172, 2019). "About half of the neurodegenerative disease-associated genes, namely APP, PSEN1, and PSEN2 for AD; C9orf72 and MAPT for FTD and SNCA; and PRKN and PARK7 for PD, have larger number of DPI robust TSSs than annotated CAT CAGE clusters." (PMID 30610612, 2019). "This manuscript will help clarify how the “cross-regulation” between TDP-43 and C9orf72 impacts autophagy and, therefore, the onset and the progression of neurodegenerative diseases such as ALS and FTLD." (PMID 28611593, 2017). "In this manuscript, we review what is known regarding the autophagic mechanism and discuss the involvement of TDP-43 and C9orf72 in autophagy and their impact on neurodegenerative diseases." (PMID 28611593, 2017). "Our literature search identified 37,991 patients diagnosed with neurodegenerative disease who were screened for the presence of the C9orf72 repeat expansion." (PMID 28522837, 2017).
neurodegenerative disease (continued). "Since multiple studies have reported that the hexanucleotide repeat expansion led to reduced expression of C9orf72 mRNAs and proteins in patient cells and brains, the defects associated with loss of C9orf72 protein function could contribute to the pathogenesis of relevant neurodegenerative diseases." (PMID 27875531, 2016). "It has been recently reported that binding of NCL to the endogenous (GGGGCC)n hexanucleotide repeat expansion (HRE) in C9orf72 is responsible for the initiation of molecular cascades that lead to neurodegenerative diseases." (PMID 26354862, 2015). "This makes it challenging to determine whether the pathology seen was indeed caused by the C9orf72 transgene and highlights how the FVB/N strain might be unsuitable for use in modelling neurodegenerative diseases." (PMID 39945358, 2025). "As noted in this review, sporadic neurodegenerative diseases were present in some boxers, while one case had features suggesting autosomal dominant disease and another case had a family history of ALS and a C9orf72 mutation." (PMID 40722320, 2025). "Furthermore, the cell-to-cell transmission of neurodegenerative disease-associated protein oligomers, such as TDP-43 and ALS-associated and aggregation-prone dipeptide repeat peptides transcribed from the C9orf72 locus, has been demonstrated." (PMID 38902525, 2024). "In recent years, the role of C9orf72 in neurodegenerative diseases has received increasing attention, with reports of its expression changes in AD and ALS,5, 6, 7 albeit the specific underlying mechanism remains unclear." (PMID 37353944, 2023). "Beyond C9ORF72-mediated FTD, we anticipate this model may be useful to interrogate newly identified risk factors and disease modifiers in other neurodegenerative diseases." (PMID 37614226, 2023). "Chromosome 9 open reading frame 72 (C9orf72) is one of the most dazzling molecules in neurodegenerative diseases, albeit that its role in Parkinson's disease (PD) remains unknown." (PMID 37353944, 2023). "We described an earlier disease onset in GRN/C9orf72 pedigrees in subjects carrying the p.Asn521Thr variant in PTEN-induced kinase 1 (PINK1), thus highlighting a gene already known to be strongly involved in various neurodegenerative diseases." (PMID 36361641, 2022). "Furthermore, we discuss how the potential for formation of iG4s in neuronal cells, triggered by repeat expansions in the C9orf72 gene, can lead to the formation of nucleic-acids based pathological aggregates in neurodegenerative diseases like ALS and FTD." (PMID 36281554, 2022). "However, another study showed that the role of intermediate repeat copies is closely related to neurodegenerative diseases and C9ORF72 expression." (PMID 33390807, 2021). "Therefore, understanding how C9ORF72 leads to neurodegenerative diseases is important for the identification of treatments for neurodegenerative diseases." (PMID 33390807, 2021). "Taken together, our findings suggest that the C9orf72 protein plays a role in key nutrient-sensing and metabolic processes, and its dysregulation may contribute to age-dependent neurodegenerative diseases." (PMID 32282804, 2020). "In the present study we showed that mutations in TARDBP and C9ORF72 genes, associated to defects in RNA metabolism in ALS and FTD neurodegenerative diseases, affect mitochondria functionality by altering several morphological and bioenergetics parameters in a gene-specific manner." (PMID 27151080, 2016).
neurodegenerative disease (continued). "Given that neurodegenerative diseases in general are characterized by mitochondrial and respiratory malfunctions, the role of C9orf72 DNA and RNA in heme sequestration as well as its inappropriate activation in ALS and FTD neurons may warrant examination." (PMID 25207541, 2014). "In turn, this will accelerate the speed with which disease prevention trials, whether using a traditional or master protocol (e.g. platform or basket designs), can be initiated—thus bringing us closer to the ultimate goal of preventing C9orf72-related neurodegenerative disease." (PMID 40794569, 2025). "Many neurodegenerative disease-associated aggregation-prone proteins, such as α-synuclein, FUSP525L, TDP-43, amyloid beta, and C9ORF72-associated poly(GR) dipeptide, are detected in mitochondria of human patients or disease models and impair mitochondrial functions." (PMID 38900507, 2024). "For clinical validation, PGRN levels were measured in plasma from 32 cognitively healthy individuals, 52 confirmed GRN mutation carriers, 25 C9orf72 mutation carriers and 216 patients with different neurodegenerative diseases of which 70 were confirmed as non-mutation carriers." (PMID 37476993, 2023). "However, the identification of a progressive MS patient with a pathogenic C9orf72 expansion and probable co-existing with FTD highlights the complexity and challenges involved in recognizing distinct neurodegenerative diseases that may co-occur in MS patients." (PMID 37511014, 2023). "In view of the important position of C9orf72 repeat expansion in ALS and FTD, uncovering the mystery of C9orf72C9-associated ALS/FTD will help us find effective therapeutic targets, thereby having a significant influence on patients suffering from these debilitating neurodegenerative diseases." (PMID 32983232, 2020). "SQSTM1 showed a behavior similar to that of RE C9orf72, sharing with the major ALS genes a young AAO of the affected patients, but with a rare family history for other neurodegenerative diseases." (PMID 33770234, 2021). "Therefore, given the C9orf72 gene transcripts are most abundant in the brain of human post‐mortem tissue, it may not be surprising that C9orf72 NRE DPRs are more readily detected within these regions that are directly linked to neurodegenerative disease." (PMID 30617154, 2019). "Furthermore, the prevalence of family history for all neurodegenerative diseases in the C9ALS cohort reached 81.82%, underscoring the broader role of C9ORF72 in neurodegeneration." (PMID 40149460, 2025). "This indicates that C9orf72 loss of function is not sufficient to lead to ALS/FTD, further highlighting the complex nature of these neurodegenerative diseases." (PMID 38318532, 2024). "C9orf72-specific up-regulated protein change revealed the involvement of the TOR pathway (online resource), meanwhile FUS and SOD1 shared common features in terms of RNA processing and neurodegenerative diseases-related pathways (online resource)." (PMID 37488208, 2023). "The identification of an expansion of the hexanucleotide repeat GGGGCC (or G4C2) in intron 1 of the C9orf72 gene has opened a new field of investigation on long non-coding RNAs and neurodegenerative diseases." (PMID 34140881, 2021). "We also demonstrate that HARDEN is not specific to the C9orf72 locus, but can be used to methylate the neurodegenerative disease gene APP as well." (PMID 31680172, 2019). "Subjects were screened for C9orf72 repeat expansions, GRN and MAPT mutations, and, if negative, mutations in other neurodegenerative disease genes, by whole-exome sequencing (WES) (n = 108), including WES-based copy-number variant (CNV) analysis." (PMID 28749476, 2018). "Besides rapamycin, the increasing identification of a range of drugs that appear to boost autophagy may be of relevance, not only to C9orf72-ALS, but also to many other neurodegenerative diseases." (PMID 37083530, 2023).
neurodegenerative disease (continued). "Moreover, NTF1 does not stain ubiquitinated inclusions in two different neurodegenerative disease cases, SCA3 and C9ORF72 associated ALS/FTD." (PMID 31665086, 2019). "For quantitative RT-PCR analysis for the three known C9orf72 transcripts, we extracted RNA from the frontal cortex of the proband, three heterozygous C9orf72 FTD cases and four pathologically confirmed controls without neurodegenerative disease." (PMID 23818065, 2013).